SAMD4B (sterile alpha motif domain containing 4B)
Diseases named in the same sentence as SAMD4B in open-access papers:
SAMD4B is named in the same sentence as 10 diseases in open-access papers, as found by Europe PMC text mining. Sharing a sentence is not in itself a finding about the gene and the disease. The quoted sentences say what the papers report.
colorectal cancer (3 papers, 2023 to 2025). A primary or metastatic malignant neoplasm that affects the colon or rectum. "SAMD4B is confirmed as a direct target of miR-451, and miR-451 inhibits colorectal cancer cell malignancy by targeting the 3′-UTR of SAMD4B mRNA." (PMID 41154652, 2025). "The latest research work demonstrates that miR‐451 suppresses the malignant characteristics of colorectal cancer cells through targeting SAMD4B." (PMID 36732864, 2023). "For instance, it is found that SAMD4 is highly expressed in ovarian cancer and SAMD4B is also highly expressed in colorectal cancer, while SAMD4A is low expressed in breast cancer and SAMD4A is also correlated to the development of oral cancer." (PMID 36732864, 2023). "Conversely, overexpression of SAMD4B attenuated miR-451-induced apoptosis and promoted colorectal cancer progression." (PMID 36732864, 2023). "MiR-451, on the other hand, could inhibit the malignant phenotypes of colorectal cancer cells by decreasing the expression of sterile alpha motif domain containing 4B (SAMD4B) to decrease carcinogenesis in vitro and in vivo." (PMID 39736850, 2025). "Dual luciferase reporter assay validated that miR-451 could specifically bind to the 3’-UTR of SAMD4B mRNA to down-regulate the expression of SAMD4B, thus inhibiting proliferation and promoting apoptosis of colorectal cancer cells." (PMID 36732864, 2023). "This study suggests that miR-451/SAMD4B axis may serve as a new therapeutic target for the treatment of patients with colorectal cancer." (PMID 36732864, 2023).
breast carcinoma (2 papers, 2024 to 2025). "To clarify the mechanism underlying SAMD4B-mediated promotion of breast cancer cell growth and proliferation, we investigated its role in regulating cell cycle progression." (PMID 41154652, 2025). "Although our in vitro results clearly indicate that SAMD4B enhances metastatic phenotypes of breast cancer cells, these findings cannot reflect the complexity of the tumor microenvironment in vivo." (PMID 41154652, 2025). "Our data showed that SAMD4B knockdown significantly suppressed the proliferative capacity of breast cancer cells." (PMID 41154652, 2025). "We next evaluated the impact of XAV-939-mediated Wnt/β-catenin pathway inhibition on the proliferative and metastatic phenotype of SAMD4B-overexpressing breast cancer cells." (PMID 41154652, 2025). "We first validated the capacity of XAV-939 to block SAMD4B overexpression-induced activation of the Wnt/β-catenin pathway in breast cancer cells." (PMID 41154652, 2025). "Consistent with the MTT results, SAMD4B knockdown reduced the colony-forming ability of breast cancer cells compared with the control group, whereas SAMD4B overexpression resulted in a significant increase in the colony-forming capacity of breast cancer cells." (PMID 41154652, 2025). "Taken together with our previous observations, these pharmacological inhibition experiments substantiate that SAMD4B enhances the proliferative and metastatic capacities of breast cancer cells primarily via activation of the Wnt/β-catenin pathway." (PMID 41154652, 2025). "Our findings demonstrated that SAMD4B promotes breast cancer cell proliferation, metastasis, and the G1-S phase transition of the breast cancer cell cycle through the activation of the Wnt/β-catenin signaling pathway." (PMID 41154652, 2025). "The results showed that the SAMD4B mRNA expression level was significantly higher in breast cancer tissues than in normal breast tissues, contrasting with the previously reported low SAMD4A expression in breast cancer." (PMID 41154652, 2025). "SAMD4B facilitates the G1-to-S phase transition in the breast cancer cell cycle and profoundly modulates the protein expression of G1 phase-specific cyclins and CDKs." (PMID 41154652, 2025). "Our findings demonstrate that SAMD4B promotes breast cancer cell proliferation and metastasis through the induction of EMT, which provides key insights into the molecular mechanism underlying breast cancer metastasis." (PMID 41154652, 2025). "The results demonstrated that SAMD4B knockdown substantially suppressed the invasiveness of breast cancer cells, whereas SAMD4B overexpression significantly promoted this phenotype." (PMID 41154652, 2025). "This oncogenic role of SAMD4B is functionally analogous to that of the known scaffolding protein in breast cancer pathogenesis." (PMID 41154652, 2025). "In conclusion, SAMD4B promotes EMT of breast cancer cells at least partly by activating the Wnt/β-catenin pathway, thereby facilitating tumorigenesis and metastasis." (PMID 41154652, 2025). "Western Blot analysis demonstrated that SAMD4B depletion significantly reduced the expression of G1 phase-specific Cyclin E-CDK2 and Cyclin D1-CDK4 complexes in breast cancer cells, while SAMD4B overexpression remarkably upregulated these complexes." (PMID 41154652, 2025). "Collectively, these complementary experimental results strongly support the conclusion that SAMD4B activates the Wnt/β-catenin signaling pathway in breast cancer cells." (PMID 41154652, 2025).
breast carcinoma (continued). "Collectively, these findings establish that SAMD4B facilitates breast cancer cell proliferation by upregulating G1-phase Cyclin-CDK complexes, thereby accelerating G1-S phase transition and driving cell cycle progression." (PMID 41154652, 2025). "RT-qPCR analysis results demonstrated that knockdown of SAMD4B significantly downregulated β-catenin mRNA level, whereas its overexpression markedly upregulated β-catenin mRNA expression in breast cancer cells." (PMID 41154652, 2025). "Despite these findings establishing an indirect involvement of SAMD4B in tumorigenesis, its specific function and the molecular regulatory mechanisms in breast cancer pathogenesis remain unelucidated." (PMID 41154652, 2025). "We next performed RT-qPCR and Western Blot analyses to verify SAMD4B expression in breast cancer cell lines." (PMID 41154652, 2025). "Previous studies have established SAMD4A as a tumor suppressor that is downregulated in breast cancer, while the function of SAMD4B in tumorigenesis remains poorly defined." (PMID 41154652, 2025). "Collectively, these findings strongly support the oncogenic role of SAMD4B and validate it as a promising therapeutic target for breast cancer intervention." (PMID 41154652, 2025). "Compared with the normal breast epithelial cell line MCF-10A, both MCF-7 and MDA-MB-231 breast cancer cell lines exhibited significant upregulation of SAMD4B at the mRNA and protein levels." (PMID 41154652, 2025). "Conversely, SAMD4B overexpression accelerated wound closure, yielding smaller scratch areas compared to control cells in both cell lines, suggesting that SAMD4B promotes migratory capacity in breast cancer cells." (PMID 41154652, 2025). "To evaluate the potential prognostic relevance of SAMD4B in breast cancer, we performed the Kaplan–Meier survival analysis using multiple databases, including Kaplan–Meier Plotter, UALCAN, GEPIA, and OncoDB." (PMID 41154652, 2025). "These collective data identify SAMD4B as a pro-metastatic oncogene that promotes the migration and invasion of breast cancer cells." (PMID 41154652, 2025). "Conversely, SAMD4B overexpression markedly enhanced the proliferative potential of these two breast cancer cells." (PMID 41154652, 2025). "To assess SAMD4B’s role in breast cancer metastatic progression, we first conducted wound healing assays." (PMID 41154652, 2025). "Functional assays demonstrated that SAMD4B facilitated breast cancer cell proliferation, migration, and invasion by inducing epithelial–mesenchymal transition (EMT)." (PMID 41154652, 2025). "To delineate the function of SAMD4B in breast cancer cell proliferation, we first utilized the MTT assay to evaluate how SAMD4B modulates the proliferative activity of breast cancer cells." (PMID 41154652, 2025). "To explore the biological function of SAMD4B in breast cancer progression, we first established stable breast cancer cell lines with SAMD4B knockdown or overexpression via lentivirus-mediated infection." (PMID 41154652, 2025). "In summary, our findings clarify that SAMD4B exerts an oncogenic role in breast cancer progression by activating the Wnt/β-catenin pathway." (PMID 41154652, 2025). "To address this, we initially analyzed SAMD4B expression in breast cancer tissues using the TCGA database via the UALCAN tool." (PMID 41154652, 2025). "Together, these data further confirm that SAMD4B activates the Wnt/β-catenin pathway in breast cancer cells." (PMID 41154652, 2025). "In our present work, we comprehensively investigated the functional role and molecular regulatory mechanisms of SAMD4B in the process of breast cancer initiation and progression." (PMID 41154652, 2025).
breast carcinoma (continued). "A notable limitation of the current study lacks sufficient in vivo validation using animal models to verify the oncogenic function of SAMD4B in promoting breast cancer metastasis." (PMID 41154652, 2025). "Flow cytometric analysis revealed that SAMD4B knockdown significantly increased the accumulation of breast cancer cells in the G0/G1 phase, along with a corresponding decrease in the number of cells in the S phase." (PMID 41154652, 2025). "SAMD4B overexpression increased Topflash luciferase activity and upregulated the expression of β-catenin, Axin2, Cyclin D1, and c-Myc in breast cancer cells." (PMID 41154652, 2025). "Our study is the first to establish an oncogenic role for SAMD4B in breast cancer, providing new mechanistic insights into breast cancer progression." (PMID 41154652, 2025). "To uncover the molecular mechanism through which SAMD4B activates the Wnt/β-catenin signaling pathway in breast cancer, we next investigated its regulatory effect on the mRNA expression of β-catenin, a central effector of the pathway." (PMID 41154652, 2025). "Although our research advances understanding of SAMD4B’s oncogenic role in breast cancer progression, further in vivo investigations are required to clarify its specific molecular mechanisms in tumorigenesis and metastasis." (PMID 41154652, 2025). "Collectively, these complementary experimental data establish SAMD4B as a key promoter in the growth and proliferation of breast cancer cells." (PMID 41154652, 2025). "Therefore, further in vivo investigations are warranted to validate the pro-metastatic function of SAMD4B in breast cancer." (PMID 41154652, 2025). "Taken together, our research identifies that SAMD4B exerts an oncogenic role in promoting breast cancer progression via activating the Wnt/β-catenin signaling pathway, highlighting its potential as a novel therapeutic target for breast cancer." (PMID 41154652, 2025). "In contrast, the expression pattern and functional relevance of its homolog, SAMD4B, in breast cancer remain unknown." (PMID 41154652, 2025). "In this study, we observed that SAMD4B expression is upregulated in breast cancer." (PMID 41154652, 2025). "We therefore investigated the regulatory role of SAMD4B in EMT of breast cancer cells." (PMID 41154652, 2025). "Nevertheless, the function of SAMD4B in breast cancer is largely unexplored." (PMID 41154652, 2025). "In summary, our in vitro findings establish that SAMD4B acts as a novel oncogene in breast cancer." (PMID 41154652, 2025). "Our results revealed that the β-catenin transcript was significantly enriched in SAMD4B-immunoprecipitates compared to control IgG-immunoprecipitates in both MCF-7 and MDA-MB-231 breast cancer cells, demonstrating a specific physical interaction between SAMD4B protein and β-catenin mRNA." (PMID 41154652, 2025). "Functional assays confirmed the oncogenic role of SAMD4B in breast cancer pathogenesis." (PMID 41154652, 2025). "Therefore, our study is the first to systematically investigate the functional role and specific molecular mechanisms of SAMD4B in breast cancer progression." (PMID 41154652, 2025). "Additionally, XAV-939 abrogated SAMD4B-driven promotion of breast cancer cell proliferation, migration, invasion, and EMT." (PMID 41154652, 2025).
breast carcinoma (continued). "In addition, we investigated the subcellular localization of SAMD4B in breast cancer cells." (PMID 41154652, 2025). "Taken together, our data demonstrate that SAMD4B enhances the aggressive phenotype of breast cancer cells by inducing EMT and upregulating MMPs, thereby promoting breast cancer cell proliferation and metastasis." (PMID 41154652, 2025). "Specifically, knockdown of SAMD4B significantly inhibited the proliferation, migration, invasion, EMT, and induced cell cycle arrest of breast cancer cells, while its overexpression robustly promoted these malignant phenotypes." (PMID 41154652, 2025). "Our data demonstrated that SAMD4B overexpression downregulated E-cadherin while upregulating N-cadherin, Vimentin, Snail, and Slug, suggesting that SAMD4B promotes EMT in breast cancer cells." (PMID 41154652, 2025). "However, whether SAMD4B modulates EMT of breast cancer cells via this pathway remained unknown." (PMID 41154652, 2025). "In contrast, SAMD4B overexpression exhibited the opposite expression pattern of these EMT-related markers, confirming that SAMD4B promotes the migration and invasion of breast cancer cells through the induction of EMT." (PMID 41154652, 2025). "In the present study, we demonstrated that, unlike tumor suppressor SAMD4A, SAMD4B was significantly upregulated in breast cancer." (PMID 41154652, 2025). "To determine whether the promoting effects of SAMD4B on breast cancer cell migration and invasion are mediated by EMT, we detected the expression changes in EMT-related markers in breast cancer cells upon SAMD4B manipulation." (PMID 41154652, 2025). "Similarly, we found consistent results in breast cancer and colon cancer datasets, in which CD8+ T cells were significantly enriched in the low-SAMD4B-expression group." (PMID 38886351, 2024). "Despite its significance, the regulatory relationship between SAMD4B and either EMT or the Wnt/β-catenin pathway has not been reported in breast cancer." (PMID 41154652, 2025).
Obesity (2 papers, 2021 to 2023). Accumulation of substantial excess body fat. "Here, we showed that Gata6 and Samd4b are upregulated during adipocyte differentiation, which supports a role for these genes in predisposing offspring of obese fathers to diet-induced obesity in later life." (PMID 33479343, 2021). "However, additional experiments are needed to functionally validate the role of Gata6 and Samd4b in non-genetic transmission of paternal obesity." (PMID 33479343, 2021).
acute myeloid leukemia (1 paper, 2025). Acute myeloid leukemia (AML) is a group of neoplasms arising from precursor cells committed to the myeloid cell-line differentiation. "Additionally, whole-genome sequencing of patients with acute myeloid leukemia has uncovered recurrent mutations in the SAMD4B gene." (PMID 41154652, 2025).
triple-negative breast carcinoma (1 paper, 2025). An invasive breast carcinoma which is negative for expression of estrogen receptor (ER), progesterone receptor (PR), and human epidermal growth factor receptor 2 (HER2). "Interestingly, SAMD4B mRNA expression was significantly upregulated in both luminal and triple-negative breast cancer subtypes." (PMID 41154652, 2025).
cancer (3 papers, 2017 to 2024). A tumor composed of atypical neoplastic, often pleomorphic cells that invade other tissues. "Recent studies have indicated that SAMD4A and SAMD4B expressions are significantly changed in some types of cancers and associated with cancer progression." (PMID 36732864, 2023). "We found that SAMD4B was highly expressed in adjacent tissues and that the patients with high SAMD4B expression in cancer tissues had a better prognosis than those with low SAMD4B expression in adjacent tissues." (PMID 38886351, 2024). "More interestingly, seven different genes (ECH1, PEX5, MLF2, NFIX, TSPAN9, SAMD4B, and NFKBIB) were associated with another drug C646, which is a small molecule inhibitor targeting histone acetyltransferase p300, an enzyme that alters the cancer transcriptome in the lung, colon and pancreas." (PMID 29207666, 2017). "To verify this conjecture, we carried out polychromatic immunofluorescence on 8 markers, including cancer cells (CK18), T cells (CD3, CD4, CD8 and CD 29), SAMD4B, PD1 and PD-L1." (PMID 38886351, 2024).
tumor (2 papers, 2024 to 2025). "Recent research demonstrates that under sensing arginine deficiency, SAMD4B is released by Bcl2-associated athanogene 2 (BAG2) and promotes β-catenin degradation to stabilize ATF4, thereby promoting tumor cell survival." (PMID 41154652, 2025). "We further reveal the immunoregulatory mechanism of synergistic immunochemotherapy through 2’-O-Methylation modification mediated by SAMD4B, a tumour suppressor gene." (PMID 38886351, 2024). "Fewer CD29+CD8+ T cells were found in high-SAMD4B-expression patients, who had a better prognosis, thus indicating that SAMD4B improved the immune microenvironment and weakened the immune escape of tumour cells from naive CD29+CD8+ T cells." (PMID 38886351, 2024). "Among the relevant immune checkpoints, especially those expressed in tumours, only PD-L1 was affected by SAMD4B and APOA2, and its expression was positively correlated with that of APOA2." (PMID 38886351, 2024). "In addition, patients with high APOA2 and low SAMD4B expression levels had larger tumours and higher AFP levels." (PMID 38886351, 2024). "However, CD8+ T cells were enriched in tumour tissues of the low-SAMD4B-expression group." (PMID 38886351, 2024). "However, the biological function of SAMD4B in tumor metastasis remains unclear." (PMID 41154652, 2025). "We simultaneously ectopically expressed Myc-tagged SAMD4B, Flag-tagged APOA2 and HA-tagged immune checkpoints that are mainly expressed in tumours (PD-L1, PD-L2, FGL1 or HMGB1) and demonstrated that overexpression of SAMD4B could reduce the protein level of APOA2." (PMID 38886351, 2024). "However, high SAMD4B expression could increase the instability of APOA2 mRNA, further reducing PD-L1, and thus weakening the immune escape of tumour cells from naive CD29+CD8+ T cells." (PMID 38886351, 2024).
SAMD4B also shares sentences with these, for which no sentence is quoted: infection (2 papers); colon cancer (1); melanoma (1).